EGF (epidermal growth factor)
Diseases named in the same sentence as EGF in open-access papers (continued):
Sharing a sentence is not in itself a finding about the gene and the disease.
prostate carcinoma (204 papers, 1990 to 2025). A carcinoma that arises from epithelial cells of the prostate gland. "Recently, Randox Laboratories have developed a multiplex test (Prostate Cancer Risk Biochip) which can simultaneously measure the levels of IL-8, EGF, MCP-1 and tPSA from a single serum sample." (PMID 40702125, 2025). "Our data suggests that a new diagnostic and therapeutic approach for managing prostate cancer patients is primarily related to the changes of EGF regulation in YB-1/ERK axis." (PMID 34696665, 2021). "EGF induced growth of prostate cancer LNCaP cell has been associated with the expression of sarcoendoplasmic reticulum calcium ATPase 2b (SERCA2b) and the calcium pool content, measured by thapsigardine-induced calcium release." (PMID 26398212, 2015). "Markedly, our data demonstrate that the activated EGFR signaling-induced autocrine AREG, EREG, and TGFA expression in Ras-mutated prostate cancer cells is associated with a down-regulation in miR-203 expression level in an EGF-dependent manner." (PMID 25004126, 2014). "This stabilization of F-actin polymerization upon EGF-stimulation was associated with increased migration, lamellipodia and filopodia formation in prostate cancer cells." (PMID 24040362, 2013). "In addition, five prostate cancer–associated genes (EGF, PIK3R1, ATM, BRCA1, and BRCA2) with apparent damaging mutations, one of which is a rare mutation in ATM, a possible therapeutic target, further support this claim." (PMID 36643868, 2022). "However, although EGFR overexpression and EGF signaling constitutive activation in prostate cancer are associated with poor prognosis, the exact role played by EGF/EGFR in the progression and development of this disease still needs to be elucidated." (PMID 28430640, 2017). "Given the critical role of Ras mutation-induced EGFR signaling activation in prostate cancer progression, we hypothesized that EGF-induced autocrine AREG, EREG, and TGFA expression might be directly mediated by miR-203 in RasB1 cells." (PMID 25004126, 2014). "A biomarker-based (tPSA, EGF, MCP-1, IL-8) prostate cancer risk score (PCRS) was then applied to a retrospective cohort (n = 1,142/25,356) of individuals to assess PCa risk." (PMID 40702125, 2025). "ERBB2 recruitment enhances PI3K/AKT signaling in prostate cancer cells, serving as a key mediator of EGF-induced proliferation." (PMID 41331197, 2025). "For example, OPN promoted human prostate cancer cells only when epidermal growth factor was also presented to the cells." (PMID 40453761, 2025). "In contrast, the survival ability of prostate cancer patients indicated that CCL18 is more potential than the EGF." (PMID 40692603, 2025). "It downregulates CDK4/6 to suppress growth in osteosarcoma, and curbs proliferation triggered by epidermal growth factor (EGF) in prostate cancer." (PMID 40565167, 2025). "ADAM10 is known for its shedding activity, particularly in the release of EGFR ligands, and is upregulated in response to EGF and IGF-I, both of which are implicated in aggressive prostate cancer." (PMID 41614805, 2025). "Previously, we showed that Gαi2 plays a critical role in oxytocin (OXT) and EGF signaling to induce cell migration in prostate cancer cells." (PMID 40141305, 2025). "Second, the knockdown and or knockout of endogenous Gαi2 in prostate cancer cells induced an attenuation of EGF-dependent cell migration and invasion." (PMID 40141305, 2025). "A published study has reported that in prostate cancer, the epidermal growth factor can stimulate the degradation of EPLIN through the ubiquitin–proteasome system." (PMID 38732188, 2024). "We have disclosed previously that compound 14 attenuated the EGF-induced migration of prostate cancer cell lines PC3 and DU145." (PMID 38254786, 2024). "A Chip assay generated data revelled the binding of EGF/EGFR complex to the promoter of CYP27B1 in PZ‐HPV7 cells which leads to prostate cancer development." (PMID 39434198, 2024).
prostate carcinoma (continued). "Combination of EGF-PE24mutΔREDLK with SO1861 resulted in synergistic cytotoxic effects in prostate cancer cells and was even more effective than the targeted toxin containing the PE24mut domain." (PMID 37859824, 2023). "In all prostate cancer cell lines, the cytotoxic effect of EGF-PE24mut-ΔREDLK was not only reconstituted, but also multiplied by endosomal escape enhancement, despite its at least 11-fold lower intrinsic toxicity compared to EGF-PE24mut." (PMID 37859824, 2023). "Consistently, in prostate cancer cells, TGF-β- and epidermal growth factor (EGF)-induced EMT phenotypes were found to be associated with downregulation of human leukocyte antigen (HLA)-I." (PMID 36823234, 2023). "Binding of EGF-PE24mut and EGF-PE24mutΔREDLK to prostate cancer cells was determined by flow cytometry." (PMID 37859824, 2023). "The aim of the present study was to optimize the efficacy of the targeted toxin EGF-PE24mut for the treatment of prostate cancer." (PMID 37859824, 2023). "Addition of 1 μg/ml of the endosomal escape enhancer SO1861 led to a 4- to 150-fold enhanced cytotoxicity of EGF-PE24mut and even to a more than 26.2- to 6,966-fold enhanced cytotoxicity of EGF-PE24mutΔREDLK in the prostate cancer cell lines." (PMID 37859824, 2023). "For instance, PGG hindered the growth of prostate cancer cells by inhibiting epidermal growth factor (EGF)-induced nuclear translocation of NF-κB and subsequent activation of c-Jun N-terminal kinase (JNK), an upstream modulator of NF-κB." (PMID 37375411, 2023). "The combined application of EGF-PE24mutΔREDLK and SO1861 on prostate cancer cells led to a 16- to 300-fold enhanced cytotoxicity compared to EGF-PE24mut." (PMID 37859824, 2023). "In the present study, we generated the new targeted toxin EGF-PE24mutΔREDLK binding to the epidermal growth factor receptor (EGFR) on the surface of prostate cancer cells." (PMID 37859824, 2023). "Incubation of the prostate cancer cells with EGF-PE24mutΔREDLK and SO1861 resulted in a complete inhibition of protein biosynthesis after 48 or 72 h, respectively." (PMID 37859824, 2023). "It has been proven that fisetin significantly enhanced the levels of E-cadherin in EGF-treated prostate cancer cells." (PMID 37996895, 2023). "IP3R1 is involved in resistance to apoptosis in prostate cancer cells and in the epithelial–mesenchymal transition induced by epidermal growth factor in the MDA-MB-468 human BC cell line." (PMID 35328381, 2022). "Involved in cell proliferation and tumor growth, Ki67 proteins and epidermal growth factor (EGF) are used as important predictive markers in patients with prostate cancer." (PMID 35681707, 2022). "Previous in vitro studies have shown that FOXA1 increases pro-angiogenic factors, including EGF, endothelin-1, and endoglin in prostate cancer cells and promotes endothelial cell proliferation, migration, and tube formation." (PMID 35627227, 2022). "HSP27 is required for EGF‐mediated EMT via modulation of the β‐catenin/Slug signaling pathway in prostate cancer." (PMID 35928554, 2022). "As a member of growth factors, EGF is highly expressed in various cancers, including prostate cancer." (PMID 34069970, 2021). "Another study found that a 3-day treatment of prostate cancer cells with JZL184 resulted in an increase in cell density under basal conditions but a decrease in epidermal growth factor (EGF)-induced proliferation." (PMID 34830856, 2021). "Our findings provide new insights into molecular controls of EGF and the development of potential therapeutics targeting δ-catenin to control prostate cancer progression." (PMID 34069970, 2021). "Various factors, such as hepatocyte growth factor (HGF) and epidermal growth factor (EGF) that are altered in the prostate cancer microenvironment through increased production by tumor cells or the cancer-associated stroma are candidates for eliciting EMT." (PMID 34831167, 2021).
prostate carcinoma (continued). "In follow-up clinical trials, we can investigate several approaches to target AKT/δ-catenin/p21 to attenuate EGF signaling in prostate cancer." (PMID 34069970, 2021). "This fragment reduces Vimentin promoter luciferase activity, membrane localization and intensity of AKT-PH domain upon EGF stimulation, focus formation and migration of prostate cancer cells." (PMID 34706306, 2021). "Positive and negative regulation of YB-1 and CXCL14 was observed after EGF treatment in prostate cancer cells, respectively." (PMID 34696665, 2021). "Considering the function of EGF in prostate cancer, uncovering the mechanism of δ-catenin involved in EGF regulation is particularly important." (PMID 34069970, 2021). "For example, in MCF-7 cells, a proliferative role of WISP2 has been reported in which silencing WISP2 inhibited cell proliferation induced by serum and epidermal growth factor, whereas it acts as a growth repressor in prostate cancer cells." (PMID 32711570, 2020). "Previously, we have shown that Gαi2 plays a critical role in oxytocin (OXT) and EGF signaling, to induce the cell migration of prostate cancer cells." (PMID 32575572, 2020). "Activation of EGFR by the epidermal growth factor (EGF) has been shown to promote prostate cancer growth, while suppressing the PSA production and secretion in the EGF stimulated cells." (PMID 32085441, 2020). "DHT increases both epidermal growth factor receptor (EGFR) numbers and receptor–ligand affinity in androgen-sensitive prostate cancer cells; this correlates with increased EGF binding and an enhanced mitogenic response to EGF." (PMID 32326308, 2020). "Previously, we found that endogenous Gαi2 is essential for cell migration and invasion in prostate cancer cells in response to different stimuli, such as EGF, OXT, TGFβ1 and SDF-1α." (PMID 32575572, 2020). "In a human cohort of prostate cancer samples, we found that EGF is more expressed in primary tumours than either in normal tissue or in metastases." (PMID 32385236, 2020). "The underlying mechanism of ADAM9 in prostate cancer has also been discovered: ADAM9 can cleave and release epidermal growth factor and FGFR2iiib from cells, both of which play a key role in the pathogenesis of prostate cancer." (PMID 32875951, 2020). "Several signaling pathways such as estrogen receptor signaling, androgen receptor signaling, transforming growth factor beta (TGF-β) signaling and epidermal growth factor (EGF) signaling are involved in EMT in prostate cancer." (PMID 32625096, 2020). "In this study, we show that EGF-activated PI3K/Akt signalling directly regulates leucine transport in prostate cancer cells by stabilising LAT3 expression on the cell surface." (PMID 31345230, 2019). "We also assessed the effect of VM26 on the DU-145 prostate cancer cell line, characterized by an unusual decrease in EGFR level in response to EGF action in the autocrine loop, presumably associated with endocytosis." (PMID 31374910, 2019). "In another study, JZL184 was found to inhibit proliferation of prostate cancer cells exclusively when these were activated with EGF." (PMID 31143113, 2019). "It has been reported that Snail is key to the downregulation of TGF -β - and epidermal growth factor- (EGF-) induced HLA-I in prostate cancer cells, leading to the attenuation of T cell-mediated lysis." (PMID 31531020, 2019). "In this study, we firstly reported that EGF-activated PI3K/Akt signalling pathway regulates leucine uptake through the amino acid transporter LAT3 in prostate cancer." (PMID 31345230, 2019). "Using epidermal growth factor (EGF)-activated prostate cancer cells, another study was able to demonstrate AEA to inhibit proliferation by downregulation of EGF receptor expression via upstream activation of the CB1 receptor." (PMID 31143113, 2019).
prostate carcinoma (continued). "Hexane extracts of S. lappa inhibited the basal and Epidermal Growth Factor (EGF)-induced migration of prostate cancer DU145 and TRAMP-C2 cells in a dose-dependent manner (1–4 μg/mL), whereas they did not influence the viability of these cancer cells." (PMID 29495626, 2018). "hsa-mir-30a is a tumor suppressor that inhibits EMT genes that is typically down-regulated by oncogenic signals in prostate cancer like EGF, particularly in metastasis." (PMID 30557297, 2018). "Signaling through both the HGF/c-Met and EGF/EGFR is a potent inducer of cell scattering in the DU145 prostate cancer cell line." (PMID 28978320, 2017). "In prostate cancer EGF stimulates tumor progression via the coordinated ROS production, the phosphorylation of STAT3 (required for EGF-induced upregulation of HIF-1α) and the consequent induction of HIF-1α/Twist1/N-cadherin signaling pathway." (PMID 28430640, 2017). "Epidermal growth factor (EGF) has been shown to promote the stability of Snail by suppressing GSK-3beta activity in prostate cancer." (PMID 27999207, 2017). "In prostate cancer a key role for Twist1 during EGF-induced EMT and tumor invasion has been proposed since it acts as a crucial downstream mediator of these events." (PMID 28430640, 2017). "EGF signaling is critical for self-renewal of human prostate cancer stem cells by regulation of Sox2 expression." (PMID 28345658, 2017). "Previous studies in prostate cancer cells also suggest a role for miR-135a in downregulation of epidermal growth factor mediated oncogenic signaling." (PMID 29268774, 2017). "When AR signaling is lost during ADT, increased CXCR7 expression drives EGF-induced mitogenic signaling as one mechanism that potentially facilitates prostate cancer cell survival." (PMID 28596572, 2017). "A strong correlation between both Hsp27 and EGF and advanced prostate cancer, as well as with EMT through IL-6/STAT3/Twist pathway, has been reported." (PMID 28430640, 2017). "We also determined that the increased CXCR7 expression in prostate cancer cells during ADT enhances EGF-induced EGFR and ERK1/2 activation." (PMID 28596572, 2017). "In prostate cancer microenvironment Snail is able to interact not only with TGF-β but also with epidermal growth factor (EGF) in downregulating the expression of HLA-I (human leukocyte antigen class I), which influences prostate cancer progression." (PMID 28430640, 2017). "Recent data underscore the importance of the heat shock protein 27 (Hsp27) in EGF-mediated EMT in prostate cancer suggesting that EGF-induced EMT requires Hsp27 and involves β-catenin/Slug signaling pathway." (PMID 28430640, 2017). "Here we show that PI3K-C2β regulates mitogen-activated protein kinase kinase (MEK1/2) and extracellular signal-regulated kinase (ERK1/2) activation induced by foetal bovine serum (FBS) or epidermal growth factor (EGF) in prostate cancer (PCa) cell lines." (PMID 26983806, 2016). "In our study, we showed that EGF treatment significantly enhanced VGSC protein expression and siRNA-mediated knockdown of VGSC inhibited EGF-induced invasion in pII cells, which is consistent with the data obtained from the prostate cancer cells." (PMID 26718772, 2016). "IL‐8 induces the expression of chemokine receptor CXCR7, which stimulates EGF signaling to promote prostate cancer growth." (PMID 26880719, 2016). "In Mat-LyLu rat prostate cancer cells, EGF treatment (for 24 h) significantly increased VGSC current density and cell migration." (PMID 26718772, 2016). "Structurally, AR was noted to co-exist with EGFR and Src in EGF treated AR8 overexpressing prostate cancer cells." (PMID 25705125, 2015). "In prostate cancer, the activation of protein kinase C delta (PKCδ) by epidermal growth factor (EGF) increases the phosphorylation of NMIIB." (PMID 26542704, 2015).
prostate carcinoma (continued). "HIF-1α has been found to mediate EGF-induced prostate cancer cell EMT phenotype and STAT3 downstream of ROS is implicated in EGF-induced HIF-1α transcription and protein expression." (PMID 26273424, 2015). "Prostate cancer stromal cells express epidermal growth factor (EGF) as well as transforming growth factor-α (TGF-α)." (PMID 26042506, 2015). "Signaling through the epidermal growth factor (EGF) and its family of receptors (i.e., EGFR, HER2/Neu, erbB3, and erbB4) has also been implicated in the growth and progression of prostate cancer." (PMID 26566796, 2015). "Considerably enhanced tyrosine phosphorylation of AR was noted in AR8 overexpressing prostate cancer cells upon treatment with EGF." (PMID 25705125, 2015). "Investigations have shown that ligand-independent activation of the AR pathway occurs in prostate cancer, which can be enhanced by epidermal growth factor (EGF) through the signal transduction pathway." (PMID 26347776, 2015). "In this study, we report that the level of NPM1 in prostate cancer cells specifically regulates EGF expression and the MAPK (Mitogen Activated Protein Kinases) signalling pathway." (PMID 24796332, 2014). "It has been reported that direct activation of the cannabinoid CB1 receptor in epidermal growth factor (EGR)-stimulated PC-3 prostate cancer cells results in an anti-proliferative effect accompanied by a down-regulation of EGF receptors (EGFR)." (PMID 25012825, 2014). "In prostate tumors, Egr-1 expression is frequently upregulated, and Egr-1 expression in prostate cancer cells PC3 is mediated through an EGF-ERK-Elk-1 signaling cascade." (PMID 25004251, 2014). "It has been reported that EGFR was highly expressed in DU145 and PC3 cell lines which were hormone-independent human prostate cancer cell lines and responsive to EGF stimulation." (PMID 24741584, 2014). "Guo and colleagues reported that Src tyrosine kinase phosphorylated AR and conferred castration resistance to prostate cancer cells upon EGF stimulation." (PMID 23896594, 2013). "The activity of Rac1 was up-regulated over threefold after stimulation of 22Rv1 prostate cancer cells with EGF when compared to untreated cells." (PMID 24040362, 2013). "Treatment with AZA1 at 5 and 10 μM resulted in significantly reduced lamellipodia (p<0.01) and filopodia (p<0.01) formation in 22Rv1 prostate cancer cells after 24 h compared to EGF-stimulated cells." (PMID 24040362, 2013). "We identified AZA1 as a novel Rac and Cdc42 inactivating compound with significantly improved inhibition of Rac combined with additional Cdc42 inhibitory activity when used in EGF-stimulated 22Rv1 prostate cancer cells." (PMID 24040362, 2013). "Similar to the effect on 22Rv1 cells, treatment with AZA1 at 5 and 10 μM resulted in dramatically reduced filopodia formation in DU 145 prostate cancer cells after 24 h compared to EGF-stimulated cells (upper three panels)." (PMID 24040362, 2013). "Immunoblotting analyses of the F- and G-actin fractions showed that the relative expression level of F-actin/G-actin was significantly higher in EGF-stimulated 22Rv1, DU 145 and PC-3 prostate cancer cells compared to control cells (p<0.05)." (PMID 24040362, 2013). "For example, prostate cancer cells express high levels of IL-6, EGF, and EGFR, leading to constitutive activation of JAK2 or Src, which in turn results in STAT3 activation through autocrine and paracrine mechanisms." (PMID 24260381, 2013). "Activation of ErbB-1 signaling by EGF and EGF-like growth factors plays an important role in prostate cancer cell proliferation and addition of EGF to cultures of prostate cancer cells stimulates their growth." (PMID 22606295, 2012). "It has been reported that EGF is capable of inducing AR transcription and protein expression in androgen-independent prostate cancer cells." (PMID 22922989, 2012).